TENT5B (terminal nucleotidyltransferase 5B)
Description:
Catalyzes the transfer of one adenosine molecule from an ATP to an mRNA poly(A) tail bearing a 3'-OH terminal group in an ATP hydrolysis-dependent manner. May be involved in maintaining the translation efficiency of at least some genes through preventing degradation of their mRNAs. Prefers RNA molecules that are adenosine-rich close to 3'-end. In addition, may inhibit cell proliferation and cell cycle progression through ubiquitination of beta-catenin/CTNNB1.
Synonyms: FAM46B; MGC16491; FAM46
Tractability: PROTAC: ubiquitination databases record sites on it.
Gene: Protein-coding gene on chromosome 1 (27,005,020 to 27,012,850, reverse strand). Ensembl gene ENSG00000158246.
Subcellular location: Cytoplasm; Nucleus
Gene Ontology:
Molecular function: poly(A) RNA polymerase activity; protein binding
Biological process: negative regulation of apoptotic process; negative regulation of cell cycle; negative regulation of cell population proliferation; positive regulation of translation; mRNA stabilization
Cellular component: cytoplasm; nucleus
Genetic constraint (gnomAD): Loss-of-function variants: 16 observed, 24.43 expected, observed/expected ratio (o/e) 0.65, 90% interval 0.44 to 1. The upper end of that interval is the gene's LOEUF score, 1, which puts it in group 4 of 6, group 1 being the genes least tolerant of losing a copy. Missense variants: 540 observed, 602.79 expected, observed/expected ratio (o/e) 0.9, 90% interval 0.83 to 0.96. Synonymous variants: 262 observed, 268.52 expected, observed/expected ratio (o/e) 0.98, 90% interval 0.88 to 1.08.
Homologues: Orthologues: chimpanzee TENT5B (99% identical), macaque TENT5B (98% identical), pig TENT5B (92% identical), mouse Tent5b (92% identical), rat Tent5b (91% identical), guinea pig TENT5B (91% identical), rat AABR07033236.1 (89% identical), dog TENT5B (75% identical), zebrafish tent5ba (62% identical), tropical clawed frog tent5b (61% identical), zebrafish tent5bb (60% identical), Drosophila melanogaster CG46385 (50% identical), and 6 more. Paralogues in human: TENT5A (60% identical), TENT5C (58% identical), TENT5D (46% identical).
Diseases named in the same sentence as TENT5B in open-access papers:
TENT5B is named in the same sentence as 11 diseases in open-access papers, as found by Europe PMC text mining. Sharing a sentence is not in itself a finding about the gene and the disease. The quoted sentences say what the papers report.
prostate carcinoma (5 papers, 2018 to 2024). A carcinoma that arises from epithelial cells of the prostate gland. "The expression level of TENT5B is downregulated in patients with prostate cancer, and overexpression of the TENT5B gene inhibits prostate cancer cell proliferation in vitro and tumor growth in vivo." (PMID 33145994, 2021).
Infertility (1 paper, 2024). "Further research is needed to elucidate the exact reason for infertility caused by TENT5B gain-of-function." (PMID 38909026, 2024). "Additionally, TENT5B-GFP knock-in females display a gain-of-function infertility effect, with multiple chromosomal aberrations in ovulated oocytes." (PMID 38909026, 2024). "A model that provided us with additional insight into the role of TENT5B and TENT5C in oocyte biology was a mouse knock-in line expressing TENT5B with a C-terminal GFP tag (TENT5B-GFP), which, as previously stated, displayed specific infertility in females." (PMID 38909026, 2024).
leukemia (1 paper, 2026). A malignant (clonal) hematologic disorder, involving hematopoietic stem cells and characterized by the presence of primitive or atypical myeloid or lymphoid cells in the bone marrow and the blood. "Furthermore, our results also suggest that in leukemia cells, TENT4A, TENT5A, TENT5B, TENT5C, TENT5D, and TUT1 may mediate the non-templated nucleotide additions to the 3'ends of miRNAs." (PMID 42038404, 2026).
TENT5B also shares sentences with these, for which no sentence is quoted: cancer (4 papers); tumor (3); gastric cancer (2); multiple myeloma (2); glioma (1); metastatic melanoma (1); non-small cell lung carcinoma (1); ovarian carcinoma (1).